RUNX1 (RUNX family transcription factor 1)
Diseases named in the same sentence as RUNX1 in open-access papers (continued):
Sharing a sentence is not in itself a finding about the gene and the disease.
tumor (continued). "Data reported previously were used to identify differentially methylated CpGs in RUNX1 gene in tumor and matched normal tissues from 42 NSCLC patients." (PMID 32498288, 2020). "Studies towards solid tumors have indicated RUNX1 possessing a context-dependent function displayed as an oncogene or a suppressor of tumor." (PMID 32952599, 2020). "miRNA-139 acts in a tumor suppressive fashion, downregulating Runt-related transcription factor 1 (RUNX1) gene expression." (PMID 32375397, 2020). "RUNX1 is highly active in hematopoietic cell differentiation and its overexpression is necessary for tumor formation in the skin, lungs, intestines and breasts." (PMID 32746865, 2020). "H19-derived miR-675 favors the tumor progression by repressing several well-known tumor suppressor genes, such as Rb, Twist1 or RUNX1." (PMID 32610610, 2020). "RUNX1 immunopositivity was noted in all tumor types, notably in a majority of ccRCC and in all MLCRN-LMP, however, without statistical significance." (PMID 31655611, 2019). "Biochemical analyses confirmed that RUNX1 regulates established drivers of tumor initiation and the Mes subtype via microRNA (miR)-mediated interactions." (PMID 31754093, 2019). "S1D), indicating that Runx3 compensated for the tumor growth upon conditional inactivation of Runx1 in the Nf1fl/fl;DhhCre cells." (PMID 31032403, 2019). "For the establishment and maintenance of the epithelial phenotype in mammary epithelial cells, and the suppression of tumor growth, RUNX1 appears to be required as concluded from the consequences of a RUNX1 knockdown in mammary cells." (PMID 31557960, 2019). "In contrast, expression levels of RUNX1 mRNA were significantly up-regulated in tumor tissues than in healthy tissues (P<0.05)." (PMID 31015363, 2019). "In the present study we found that lncRNA-NEF was down-regulated, while Runt-related transcription factor 1 (RUNX1) was up-regulated in tumor tissues than in adjacent healthy tissues of IHCC patients." (PMID 31015363, 2019). "Expression of lncRNA-NEF and RUNX1 mRNA in tumor tissues and adjacent healthy tissues of 56 patients with IHCC was detected by RT-qPCR." (PMID 31015363, 2019). "Consistent with previous studies, our study also observed significantly up-regulated RUNX1 in tumor tissues than in healthy tissues of IHCC patients." (PMID 31015363, 2019). "A significantly reverse correlation was between the expression levels of lncRNA-NEF and RUNX1 mRNA in tumor tissues." (PMID 31015363, 2019). "Further, RUNX1, ZEB1 or TWIST1 expression didn’t show association with clinicopathological features in any of the analyzed tumor types." (PMID 31655611, 2019). "High expression of PMP22 was detected in the Runx1fl/fl;Runx3fl/fl;Nf1fl/fl;DhhCre tumor cells in intracellular structures, including Golgi body, suggesting that RUNX1/3 changes the intracellular trafficking of PMP22." (PMID 31032403, 2019). "We evaluated the effects of the RUNX1 and TGFβ/RUNX1 axis on tumor growth, and detected the tumor growth by bioluminescence analysis." (PMID 31754093, 2019). "In summary, NOTCH3 repression contributes to the tumor suppressive function of the nuclear CBFB/RUNX1 complex." (PMID 31061501, 2019). "The roles of RUNX1 have been described in many different cancers; RUNX1 is overexpressed in various epithelial tumours, especially during tumour initiation." (PMID 31370857, 2019). "While, loss of RUNX1 expression in MCF10a, an ER−ve breast epithelial cell line has been reported to induce EMT via TGFβ and Wnt signaling, suggesting that RUNX1 plays a tumor suppressor role in this ER−ve breast epithelial cell line." (PMID 29581836, 2018). "Researchers have analysed the differences in gene expression profiles of tumour and non-tumour endometrial tissues and demonstrated the overexpression of RUNX1 in invasive endometrioid carcinoma tissues." (PMID 29391048, 2018).
tumor (continued). "RUNXOR interacts epigenetically with the RUNX1 gene, which normally functions as a tumor suppressor and modulates the expression of a number of important hematopoietic regulator genes." (PMID 29914443, 2018). "Bonafide cancer-related genes of chromosome 21 amplified in the patient's tumor are RUNX1 and ERG genes." (PMID 28590426, 2017). "Reductions of Ebf1, Tcf3 and Runx1 transcripts were also detected in EB tumor cells relative to lymph node cells from Bcl-xLTg control mice, confirming that levels of these transcripts are reduced even if the tumor cells are peripheral in origin." (PMID 28692033, 2017). "In accordance with the microarray gene-expression (GSE71989 and GSE28735) results, RT–qPCR in fresh tissues also showed that RUNX1 levels were relatively higher in PDAC than in non-tumor pancreatic samples." (PMID 29245924, 2017). "The family of RUNX transcription factors (RUNX1, 2, and 3) has complex roles in development and tumor formation with both tumor-suppressive and tumor-promoting activities." (PMID 28412963, 2017). "Taken together our data demonstrate that Runx1 functions as a tumor suppressor in normal epithelial cells, by sustaining the epithelial phenotype and preserving the epithelial integrity." (PMID 28407681, 2017). "Survival analyses showed difference between RUNX1 low expression (mean of 34.7 months – 95% confidence interval, 13.92-55.48 months) and RUNX1 high expression tumor cells (mean of 14.3 months – 95% confidence interval, 9.43-19.23 months)." (PMID 29245924, 2017). "Evidence is rapidly accruing for the oncogenic and tumor suppressor functions of the Runx family of transcription factors, Runx1, Runx2 and Runx3, which are essential for normal lineage specific development." (PMID 28407681, 2017). "MiR-675 promotes tumor progression by suppressing the expression of target genes including Rb, RUNX1, TGFBI, and Twist1." (PMID 29088808, 2017). "It is propounded that the effect of RUNX1 on tumor progression was conducted with its ability to diminish ER signaling." (PMID 28747748, 2017). "In tumor cells Foxp3 low expression would explain high transcriptional activity of Runx1 on Rspo3 promoter." (PMID 26735887, 2016). "On the other hand, we transfected SCp2 non-tumor epithelial mammary cells with an expression vector containing the full length cDNA sequence of Runx1 down-stream of a CMV-promoter." (PMID 26735887, 2016). "As miRNAs directly control Runx expression and are established epigenetic regulators of cancer initiation, tumor progression, and metastasis, we postulate that miRNAs targeting Runx1 and/or Runx2 would have reciprocal expression in TRAMP prostates." (PMID 27634876, 2016). "In accord with previous reports, analysis of non-tumor bearing mice revealed lineage-dependence in permissiveness for Runx1 deletion." (PMID 27056890, 2016). "RUNX1 was downregulated in GC tissues compared to adjacent non-tumor tissues (P < 0.05), and RUNX1 reversed partial function of miR-215 in vitro." (PMID 26716895, 2016). "In other systems, miR-18a has been shown to increase the permeability of the blood–tumor barrier via RUNX1-mediated down-regulation of the tight junction-related proteins ZO-1, occludin and claudin-544." (PMID 27767041, 2016). "Through several algorithms, researchers found miR-675 regulated cell proliferation of GC cells by targeting the tumor suppression gene Runt Domain Transcription Factor 1 (RUNX1) and consisted of the H19/miR675/RUNX1 axis pathway." (PMID 27143813, 2016). "To evaluate if the observed DNA/Runx1 interaction is biologically relevant for Rspo3 expression, we altered Runx1 expression levels in tumor and normal cell lines and evaluated Rspo3 expression and cell behaviour changes." (PMID 26735887, 2016). "Normal mammary epithelial cells express higher functional levels of Foxp3 compared to tumor cells and comparable levels of endogenous Runx1 mRNA." (PMID 26735887, 2016).
tumor (continued). "Cancer metastasis due to the inhibitory effect of NIFK on the binding of RUNX1 to the CK1α promoter region, as demonstrated by our study, represents a novel tumor progression mechanism that merits further investigation." (PMID 26984280, 2016). "Potential target genes of miR-215 were predicted and RUNX1, a transcription factor and a tumor suppressor, was confirmed to be potential target according to luciferase studies." (PMID 26716895, 2016). "Depending on its expression level, RUNX1 can act as a tumor promoter or suppressor in hematological malignancies." (PMID 26910834, 2016). "It would be interesting to unravel in which steps of tumor induction and/or promotion is Runx1 and Foxp3 interplay defining cell fate." (PMID 26735887, 2016). "As the mature product of H19, H19-derived miR-675 regulated tumor cell proliferation through downregulation of its targets, tumor suppressor retinoblastoma (RB), and Runt-related transcription factor 1 (RUNX1)." (PMID 26198047, 2016). "Given the evidence from cell culture and animal models for combinatorial regulation of AXIN1 by RUNX1 and oestrogens, the analyses of the RNA-seq and the TMA data suggest ER-dependent regulation of AXIN1 by RUNX1 in patient tumours as well." (PMID 26916619, 2016). "Runx1 and Runx2 continuously increase while miRNAs with predicted or validated repression of Runx factors decrease during tumor progression." (PMID 27634876, 2016). "To address this question we studied migration capacity of DN/Runx1 (DN) transfected tumor cells (LM3 and MDA-MB-231) by in vitro scrape-wound closure assays." (PMID 26735887, 2016). "Considering the relevant contribution of the microenvironment to cancer cell growth and invasiveness, we examined the regulation of miR144 and Runx1 expression in CAFs, which are key components of the tumor microenvironment." (PMID 26030000, 2015). "As it appears that two or even the three RUNX proteins are often co-expressed in tumor cells, how does the phosphorylation of RUNX1 and RUNX3 by AKT modulate the effects of AKT-mediated RUNX2 phosphorylation on tumor progression?" (PMID 26204939, 2015). "Culturing SkBr3 cells obtained from tumor xenografts, we further confirmed the down-regulation of Runx1 protein expression upon treatment with 100nM G-1 for 3h." (PMID 26030000, 2015). "Reports have shown that RUNX1 is frequently de-regulated and has paradoxical effects in human cancers, in which it can function either as a tumor suppressor or oncogene." (PMID 26697518, 2015). "Altogether, these data suggest that G-1 stimulates the growth of SkBr3 tumor xenografts and reduces Runx1 protein expression also in vivo." (PMID 26030000, 2015). "Further confirming these results, Runx1 protein levels were found decreased in tumor xenografts upon G-1 treatment." (PMID 26030000, 2015). "The relationships between RUNX1 and clinico-pathological characteristics were examined in patients with ER– and TN tumours." (PMID 24967588, 2014). "RUNX1 expression in the tumour epithelium was determined by histoscore which takes into account the percentage of positive signal and staining intensity." (PMID 24967588, 2014). "In this scenario RUNX1 would be exerting opposing effects; dampening ER driven growth yet inducing latent tumour aggression." (PMID 24967588, 2014). "A systems biology analysis of the regulatory circuit controlled by TLX1 and TLX3 in T-ALL found these factors as master regulators and identified the runt-related TF 1 (RUNX1) as a tumor suppressor." (PMID 25428367, 2014). "Mutations in RUNX1 are commonly associated with AML but are also found in B-ALL and T-ALL, and are usually inactivating, suggesting that RUNX1 normally functions as a tumor suppressor." (PMID 23352661, 2013).
tumor (continued). "Runx1 is an experimentally validated target of miR-9 and has been reported to act as tumor suppressor, dominant oncogene or mediator of metastasis." (PMID 21857930, 2011). "Enhancer of Zeste Homolg 2 (EZH2) expression is regulated by RUNX1, STAT3 and E2F3 and high expression of EZH2 gene is associated with the tumor death and also correlated to the pathological stage." (PMID 20025723, 2009). "RUNX1 encodes the DNA-binding, alpha subunit of the core binding factor (CBF) and is viewed as a tumor suppressor gene whose haplo-insufficiency or dominant-negative mutations play a role in leukemogenesis." (PMID 18925961, 2008). "Evidence for Runx1 function as a tumor suppressor gene was obtained from knock-in mice where a single Runx1-eto fusion allele caused a similar phenotype as observed for the Runx1 null mice." (PMID 16684349, 2006). "Runx1 is also an transactivator of the p14ARF tumor suppressor, while both Runx1 and Runx2 are transcriptional repressors of the p21Cip1/Waf1 cyclin-dependent kinase inhibitor." (PMID 16076398, 2005). "Similarly, increased RUNX1 activity can promote tumor cell proliferation, migration, and invasion, as well as modulate angiogenesis and the immune microenvironment, thereby accelerating malignant progression." (PMID 40672941, 2025). "Further, analysis of sequencing data from MMRF‐CoMMpass found that POU2F2, RUNX1, and RUNX2 gene mutations were relatively rare (1.36%, 2.09%, and 0.83%, respectively) among MM patients compared to other tumor types profiled in TCGA, suggesting that their functions are preserved in MM." (PMID 40167268, 2025). "Earlier, we identified the small-molecule inhibitor 7.44 (molecular weight 341 Da), which was shown to (i) specifically interfere with NHR2, (ii) restore gene expression down-regulated by RUNX1/ETO, (iii) inhibit the proliferation, and (iv) reduce the RUNX1/ETO-related tumor growth in a mouse model." (PMID 40399488, 2025). "In line with our scRNA-seq data showing enrichment of pathways that promote tumor outgrowth in the liver and lungs, these results imply that the KLF4+ and RUNX1+ cell states associated with liver and lung metastases are selected during expansion at the respective metastatic site." (PMID 40999053, 2025). "Interestingly, RUNX1 can be toggled between tumor suppressor and a classical oncogene, by synergistic interaction with the internal tandem duplications (ITDs) in the FLT3 receptor tyrosine kinase programs." (PMID 40990016, 2025). "The negative correlation with the ossification pathway indicates that Runx1 signaling may hinder the differentiation of tumor cells, allowing them to maintain a malignant state of high proliferation and low differentiation." (PMID 40989695, 2025). "And the multi-label IF staining analysis of the tumor tissue from CRC patient suggested that the high expression of RUNX1 in tumor tissue is not caused by the abundance of macrophages." (PMID 38419056, 2024). "Nevertheless, to this day the precise mechanism guiding the RUNX1 modulated tumor angiogenesis remains unknown." (PMID 38419056, 2024). "These suggested that the characteristic of ADGRG1 as a marker for tumor-reactive T cells not only presented in RUNX1::RUNX1T1 positive AML but also might be a common feature of tumor-reactive T cells in AML." (PMID 39243082, 2024). "With these findings in our study, the sh-RUNX1 vector appears to represent a potential anti-CRC agent that might function as a suppressor on tumor growth and metastasis in CRC by silencing PTGS2." (PMID 38778047, 2024). "Moreover, RUNX1 is also aberrantly upregulated in human pituitary tumors, contributing to tumor progression." (PMID 38430423, 2024). "In keeping with previous observations, we observed syn- or metachronous myeloid non-BPDCN neoplasms in a substantial subgroup of the cohort and quite intriguingly RUNX1 mutations with VAFs suggestive of subclonal aberrations in several cases." (PMID 38600314, 2024).
tumor (continued). "Moreover, we observed a broader anti‐tumor effect of R05‐3335 compared to the siRNA‐mediated macrophage specific Runx1 inhibition in vivo." (PMID 37967345, 2024). "Similarly, elevated RUNX1 in tumour biopsies correlates with poor survival, which has been attributed to altered transcription of extracellular matrix components and remodellers." (PMID 39282259, 2024). "Also, 20 out of 24 pairs of CRC samples presented with highly expressed RUNX1 in tumor tissue, as demonstrated by the western blotting analyses." (PMID 38419056, 2024). "RUNX1, crucial in hematopoiesis, not only correlates with hematologic malignancies but also markedly influences solid tumors, as demonstrated by its elevated expression in epithelial cancers in the initial stages of tumor development." (PMID 39309442, 2024). "On the other hand, RUNX1 also acts as a tumor suppressor by inhibiting myeloid maturation." (PMID 38702444, 2024). "Inhibiting RUNX1-mediated ECM remodeling might be a potent druggable target for reversing the “cold tumor” state of GBM and enhancing the antitumor effects of immunotherapies on GBM." (PMID 38286983, 2024). "RUNX1 plays a significant role in the regulation of tumor stemness, warranting closer examination." (PMID 38430423, 2024). "These collective findings suggest that EI may exert its influence on attenuating tumor stemness attributes and reversing paclitaxel resistance in BC through the inhibition of the AR/RUNX1 signaling pathway." (PMID 38918989, 2024). "Importantly, the polarization state of macrophages stimulated by RUNX1 over-expressing tumor cells was also examined in another cell model, primary bone marrow-derived macrophage (BMDMs)." (PMID 38419056, 2024). "Importantly, interruption of RUNX1 function triggered by its expression and DNA damage has the potential to stabilize all of the oncogenic or tumor-suppressive p73 and p63 protein isoforms through downregulation of Itch." (PMID 36831211, 2023). "Moreover, we were able to analyze sequential tumor samples in 1 ETV6::RUNX1 BCP-ALL case (ALL4) who relapsed 48 months after initial diagnosis." (PMID 37469802, 2023). "Inhibition of RUNX1 also reduces tumor cell colony formation." (PMID 36766786, 2023). "At the same time, RUNX1 could contribute to the maintenance of adult stem cells in multiple epithelia, and function as a tumor suppressor in mammary epithelial cells." (PMID 37803446, 2023). "In general, RUNX1 expressed higher in tumor tissues compared to the para-tumor tissues." (PMID 37697370, 2023). "This recent evidence suggests that blocking the transcriptional activity of RUNX1 in vivo could simultaneously reduce tumor growth and increase its sensitivity to drugs, as well as weaken the pro-tumorigenic effect of the microenvironment." (PMID 36766786, 2023). "The two most frequently detected variants - CBL p.Asp460del and RUNX1 p.Glu422Ala - were described in various neoplasms, including hematologic, with no confirmed pathogenicity." (PMID 37671053, 2023). "Moreover, conditional Runx1 knockout mice have indicated the importance of RUNX1 for tumor formation in hair follicle stem cells." (PMID 36766749, 2023). "In addition, RUNX1 has been reported to mediate tumor function by transcriptionally regulating EGFR expression, activating downstream STAT3." (PMID 38057816, 2023). "On the contrary, inhibiting RUNX1 resulted in tumour enlargement and shortened overall survival." (PMID 37759525, 2023). "In summary, RUNX1 can regulate multiple pathways to regulate the function of tumor cells." (PMID 37760803, 2023). "Several mechanisms for function of RUNX1 as an oncogene or a tumor suppressor have been proposed." (PMID 37260182, 2023). "However, of the 33 different cancer types studied, many tumor types such as breast and lung cancer showed a positive correlation between the level of RUNX1 expression and prognosis." (PMID 38275375, 2023).